TSNAXIP1 (translin associated factor X interacting protein 1)
Description:
Possible role in spermatogenesis.
Synonyms: TXI1
Tractability: No criterion of Open Targets' tractability assessment is met for any kind of drug.
Gene: Protein-coding gene on chromosome 16 (67,806,765 to 67,832,148, forward strand). Ensembl gene ENSG00000102904.
Subcellular location: Cytoplasm, perinuclear region
Subcellular location (Human Protein Atlas): Nucleoplasm; Cytosol
Gene Ontology:
Molecular function: protein binding
Cellular component: cytoplasm; perinuclear region of cytoplasm
Genetic constraint (gnomAD): Loss-of-function variants: 89 observed, 86.57 expected, observed/expected ratio (o/e) 1.03, 90% interval 0.87 to 1.23. The upper end of that interval is the gene's LOEUF score, 1.23, which puts it in group 5 of 6, group 1 being the genes least tolerant of losing a copy. Missense variants: 874 observed, 921.02 expected, observed/expected ratio (o/e) 0.95, 90% interval 0.9 to 1. Synonymous variants: 347 observed, 350.71 expected, observed/expected ratio (o/e) 0.99, 90% interval 0.9 to 1.08.
Homologues: Orthologues: chimpanzee TSNAXIP1 (99% identical), macaque TSNAXIP1 (96% identical), dog TSNAXIP1 (83% identical), guinea pig TSNAXIP1 (80% identical), pig TSNAXIP1 (80% identical), rabbit TSNAXIP1 (79% identical), rat Tsnaxip1 (75% identical), mouse Tsnaxip1 (73% identical).
Diseases named in the same sentence as TSNAXIP1 in open-access papers:
TSNAXIP1 is named in the same sentence as 8 diseases in open-access papers, as found by Europe PMC text mining. Sharing a sentence is not in itself a finding about the gene and the disease. The quoted sentences say what the papers report.
breast carcinoma (1 paper, 2025). "The other IL-1β-induced proteins in 6D cells, MTUS2 and TSNAXIP1, have also been associated with the progression of breast cancer and cytoplasmic remodeling." (PMID 40429863, 2025).
tumor (3 papers, 2016 to 2023). "This yielded 88 genes associated with tumor grade, in which seven DEGs (C8orf33, TSNAXIP1, TM4SF1, CTH, ANXA2, KIAA1522 and LRRC1) can distinguish HCC of G3 from G1, two DEGs (CYB5A and RRAGD) can distinguish HCC of G3 from G2, and two DEGs (CFHR4 and F13B) can distinguish HCC of G3 from G4." (PMID 29123978, 2017).
TSNAXIP1 also shares sentences with these, for which no sentence is quoted: cocaine dependence (1 paper); gastric atrophy (1); gastric neoplasm (1); nicotine dependence (1); opioid dependence (1); schizophrenia (1).